ANGPT1 (angiopoietin 1)
Diseases named in the same sentence as ANGPT1 in open-access papers (continued):
Sharing a sentence is not in itself a finding about the gene and the disease.
diabetes (23 papers, 2012 to 2026). "Interleukin-18 receptor 1 predicted higher risk and angiopoietin-1 predicted lower risk among patients with diabetes." (PMID 37816758, 2023). "Our previous studies demonstrate that disruption of Angiopoietin-1 (Ang-1)/Tie-2 signaling pathway contributes to the diabetes-associated impairment of angiogenesis." (PMID 22454630, 2012). "Finally, in glomeruli isolated from rats with early diabetes there was a significant increase in albumin permeability and loss of endothelial glycocalyx, both of which were ameliorated by angiopoietin-1." (PMID 29433915, 2018). "We have previously demonstrated that loss of Angpt1 predisposes to an increased fibrotic response in wound-healing and in experimental diabetes, leading us to hypothesize that Angpt1 has a role in fibrogenesis." (PMID 29293543, 2018). "Conditional deletion of Angpt1 has resulted in more severe kidney injury in cases of diabetes and obstruction-induced CKD." (PMID 40952790, 2025). "Surprisingly, NCS treatment reversed the diabetes-induced reduction in Angpt1 levels, although it had only a minor effect on the elevated Angpt2 levels." (PMID 39273597, 2024). "Podocyte-specific ANGPT1 overexpression/repletion in the adult diabetic mouse led to a reduction in albuminuria and downregulation of diabetes-induced VEGFA signalling." (PMID 27207083, 2016). "In rats injected with streptozotocin, whole-kidney Angpt1 and Angpt2 mRNA and protein increase at 4 weeks’ diabetes duration, but after 8 weeks ANGPT1 levels diminish, while ANGPT2 remains elevated." (PMID 27207083, 2016). "In this study, levels of ANGPT1 were higher at baseline in T2D subjects compared to controls, consistent with its previously reported protective effects against renal disease in those with diabetes, while sTie-2 levels were similar." (PMID 41596469, 2026). "In the last few years, several publications suggest involvement of the Angpt/Tek system in several diseases with endothelial dysfunction including diabetes, sepsis, cancer, malaria and fibrosis, and increased ANGPT2/ANGPT1 levels appear to be associated with adverse outcomes." (PMID 29293543, 2018). "Furthermore, COMP-Angpt1 and podocyte-specific overexpression of Angpt1 had renoprotective roles in diabetes." (PMID 29293543, 2018). "COMP-Angpt1 and podocyte-specific overexpression of Angpt1 had renoprotective roles in diabetes." (PMID 29293543, 2018). "ANGPT1 repletion was also accompanied by a reduction in diabetes-induced nephrin phosphorylation, an event paralleled by reduced nephrin degradation and improved foot processes in the podocyte cytoskeleton/structure, leading to a more intact and functional glomerular filtration barrier." (PMID 27207083, 2016). "Overall, these observations are consistent with the contention that an increased ratio of ANGPT2/ANGPT1 could play a role in the development and progression of glomerular disease in diabetes." (PMID 27207083, 2016). "There is little data on the effects of angiopoietin-1 in adipose tissue and kidney in streptozotocin (STZ)-induced diabetes." (PMID 29212268, 2017). "We then discuss how abnormal angiogenesis develops in eyes and kidneys under diabetes condition, focusing on “VEGF uncoupling with nitric oxide” and “competitive angiopoietin 1/angiopoietin 2” mechanisms that are shared in both organs." (PMID 27313624, 2016). "Therefore, hMSC-EC secretome, particularly a cocktail of angiopoietin-1 and 2, FGF-7, MMP-9, and VEGF-C, are potential new therapeutic targets for improving wound-healing in diabetes." (PMID 35055129, 2022). "cPWWP2A directly regulates pericytes biology but indirectly regulates ECs biology via EVs carrying cPWWP2A, which inhibited miR-579 activity, increased expression of angiopoietin 1/occludin/SIRT1, and ultimately alleviates diabetes-induced retinal vascular dysfunction." (PMID 36686474, 2022). "Diabetes induced an increase in immunoreactive ANGPT2 (p < 0.05) but did not alter ANGPT1, VEGFA, VEGFB, IGFBP2 or SEMA6A." (PMID 31001672, 2019).
diabetes (continued). "We measured several plasma biomarkers of endothelial cell activation (soluble E-selectin, soluble ICAM-1 and fractalkine) and barrier function (angiopoietin-1 and angiopoietin-2), neither of which was modified in patients with diabetes mellitus." (PMID 27495247, 2016). "ANGPT2 mRNA was found to be elevated in isolated glomeruli from patients with diabetes when compared with live donor kidneys, while no change was observed in ANGPT1 expression." (PMID 27207083, 2016). "Parallel work from our group has shown that, in the very early stages of diabetic glomerulopathy (3 weeks’ diabetes duration), glomerular Angpt1 mRNA decreases in diabetic mice, with no significant changes in Angpt2 mRNA levels, when compared with non-diabetic animals." (PMID 27207083, 2016). "Previous reports have suggested that abnormal myocardial angiogenesis in the setting of diabetes may be resultant of enhanced vascular cell type death and dysregulated angiogenic growth factors and cytokines such as vascular endothelial growth factor (VEGF) and angiopoietin-1 (Ang-1)." (PMID 26682010, 2016).
Stroke (23 papers, 2009 to 2025). Sudden impairment of blood flow to a part of the brain due to occlusion or rupture of an artery to the brain. "ANGPT1 was validated to have a neural protective character in stroke because of its angiogenic and antiinflammation properties." (PMID 37409018, 2023). "GP1BA and angiopoietin-1 (ANGPT1) negatively correlated with time after stroke in females at the gene level." (PMID 33193047, 2020). "The elevated transcript levels of angiogenin and angiopoietin-1 observed after surgery imply that administering virgin coconut oil could yield neuroprotective benefits post-stroke." (PMID 40649993, 2025). "Treatment of stroke with Niaspan significantly increases Angiopoietin-1 (Ang1) expression in ischemic brain which promotes vascular stabilization and decreases brain hemorrhage and BBB leakage in T1DM rats and regulates angiogenesis as well as improves functional outcome after stroke." (PMID 24284395, 2013). "Conversely, astrocyte-secreted angiopoietin 1 promotes endothelial cell proliferation and BBB formation, thereby improving post-stroke revascularization, enhancing endogenous angiogenesis and promoting neurological functional recovery after cerebral ischemia." (PMID 36159395, 2022). "miR-320 targets ETS2, a transcription factor that regulates the expression of several genes important to leukocyte extravasation post-stroke including MMP-9, MMP-3, MMP-13, ANGPT1, and TNF." (PMID 24911610, 2014). "The vascular protection bestowed by MSCs is partly mediated by increased expression of angiopoietin-1/Tie2 and vascular endothelial growth factor/FLK1 in the animal model for stroke." (PMID 20169166, 2010). "Both angiopoietin 1 and 2 can bind to the tyrosine kinase receptor Tie-2, which is responsible for vessel maturation and stability including facilitation of smooth muscle cell/pericyte attachment and therefore could be a key promoter of revascularization after stroke." (PMID 19292924, 2009). "Furthermore, a single administration of sildenafil 24 h after a stroke increases VEGF synthesis, and acute intravenous administration of sildenafil activates VEGF and angiopoietin-1 production in the left ventricle." (PMID 35628350, 2022). "However, the damaged brain after stroke may produce many factors that can induce lymphatic inflammation, including NRP254, angiopoietin-1 and Tie-255, TGF members like BMP9-ALK156, and other DAMPs57." (PMID 31757960, 2019). "It was reported that estradiol regulates expression of ANGPT-1, but not ANGPT-2, through estrogen receptor α (ERα) in an experimental stroke model." (PMID 32409702, 2020).
endothelial dysfunction (17 papers, 2012 to 2026). In vascular diseases, endothelial dysfunction is a systemic pathological state of the endothelium (the inner lining of blood vessels) and can be broadly defined as an imbalance between vasodilating and vasoconstricting substances produced by (or acting on) the endothelium. "Elevated IL-33 on admission correlated positively with vWF-A2 and estimated glomerular filtration rate, and negatively with angiopoietin-1, suggesting links between inflammation, endothelial dysfunction, and early renal involvement." (PMID 41745779, 2026). "An angiopoietin-1 variant engineered for higher potency and stability (COMP-Ang1) has been demonstrated to improve endothelial dysfunction in various models." (PMID 37408180, 2023). "Plasma biomarkers of endothelial dysfunction (tumor necrosis factor receptor-1, angiopoietin-1 and 2) differentiated the AKI sub-phenotypes." (PMID 32680471, 2020). "To ease clinical identification of these AKI sub-phenotypes, we developed and validated a 3-variable model that included plasma markers of endothelial dysfunction (angiopoietin-1 (Ang-1) and angiopoietin-2 (Ang-2)) and inflammation (soluble tumor necrosis factor receptor-1 (sTNFR-1))." (PMID 39695715, 2024). "In quiescent endothelial cells, angiopoietin-1 stimulates Tie2, but during inflammation, angiopoietin-2 competitively inhibits Tie2, favoring endothelial dysfunction that could be targeted using adenoviral constructs expressing the protective angiopoietin-1." (PMID 32560665, 2020). "Angiopoietin-1 and -2 are biomarkers of endothelial dysfunction." (PMID 28344829, 2017). "The biomarkers were representative of several biologic processes: apoptosis (soluble Fas), inflammation (soluble tumor necrosis factor receptor 1, interleukin 6, interleukin 8) and endothelial dysfunction, (angiopoietin 1, angiopoietin 2, and soluble vascular cell adhesion molecule 1)." (PMID 28814331, 2017). "The correlation of the level of angiopoietin-1 with the level of D-dimer, a decrease in the number of platelets, and the level of fibrinogen indicates the activation of the processes of microthrombi formation and consumption of coagulation factors following endothelial dysfunction." (PMID 37238917, 2023). "While the ANGPT2 inhibition of normal ANGPT1-TIE2 signaling probably has a role in endothelial dysfunction and coagulopathy, it was also shown in vitro that ANGPT2, and to a lower extent ANGPT1, can bind and inhibit the function of thrombomodulin (TM)." (PMID 35740360, 2022). "ANGPT1, a key regulator of vascular homeostasis, may promote NAFLD progression by modulating hepatic angiogenesis and endothelial dysfunction, exacerbating steatosis and fibrosis." (PMID 40756562, 2025). "Given the significant correlations of angiopoietin-1 with the levels of acute phase reactants, as well as the degree of lymphopenia, it is possible to assume the effect of proinflammatory cytokines and the SARS-CoV-2 itself on the endothelium with its damage and consequent endothelial dysfunction." (PMID 37238917, 2023). "Overall, cadherin-5 and sTie-2, together with increases in P-selectin, ICAM3, ANGPT1 and PAI-1, suggest that hypoglycemia may result in a shift from endothelial stability to an inflammatory, pro-adhesive and pro-thrombotic phenotype, indicating worsening endothelial dysfunction after baseline." (PMID 41596469, 2026). "Moreover, a higher angiopoietin-2/angiopoietin-1 balance, indicating endothelial activation, at pre-LD was identified in patients subsequently developing ICANS, suggesting endothelial dysfunction prior to CAR T-cell therapy could influence the occurrence of toxicity." (PMID 38001703, 2023).
glaucoma (15 papers, 2018 to 2025). Increased pressure in the eyeball due to obstruction of the outflow of aqueous humor. "This is also true in patients heterozygous for TIE2 and ANGPT1 loss-of-function mutations who have been diagnosed with glaucoma." (PMID 36190459, 2022). "Meanwhile, Tie2-activating antibody (ABTAA) rescues the phenotype of glaucoma in double Angpt1/Angpt2-deficient mice, raising the possibility that this signaling pathway could be an interesting therapeutic target for the treatment of glaucoma." (PMID 37091974, 2023). "A root cause for the development and progression of primary open-angle glaucoma might be the loss of the Schlemm’s canal (SC) cell function due to an impaired Angiopoietin-1 (Angpt-1)/Tie2 signaling." (PMID 35056075, 2021). "We next examined Angpt1ΔNC mice for signs of glaucoma, to determine if neural crest specific Angpt1 deletion was sufficient to recapitulate the phenotype of inducible whole-body knockouts." (PMID 34663817, 2021). "Using neural crest-specific Wnt1-cre, we have shown that deletion of Angpt1 in the uveal tract recapitulates the glaucoma phenotype of whole-body knockouts, confirming the TM origin of SC-regulating ANGPT1." (PMID 34663817, 2021). "Heterozygous loss of function variants in TEK or its primary ligand ANGPT1 have been linked to PCG in children, and ANGPT1 and ANGPT2 have been associated with primary open-angle glaucoma (POAG) in adults." (PMID 34663817, 2021). "Here, the authors show that deletion of these genes induces glaucoma in mice, and that activation of ANGPT1-TEK signaling ameliorates disease progression in mouse models." (PMID 34663817, 2021). "Loss of function variants in TEK, or its trabecular meshwork (TM)-expressed ligand ANGPT1 cause primary congenital glaucoma (PCG), a severe form of pediatric glaucoma, in humans and mice and are associated with increased risk of primary open angle glaucoma (POAG) in adults." (PMID 41279337, 2025). "Their study’s clinical utility lies in the identification of ANGPT1-TEK signalling as a potential glaucoma therapy target and demonstrating that a recombinant ANGPT1-mimetic fusion protein can reduces IOP elevation and retinal ganglion cell (RGC) loss in a murine PGC model." (PMID 37138096, 2023). "Emphasizing the potential of these signaling molecules as novel glaucoma therapies, we found that an ANGPT1-mimetic could specifically induce developmental SC remodeling and growth in wild-type and Angpt1ΔNC eyes and lower IOP in healthy adult eyes without pathological angiogenesis." (PMID 34663817, 2021). "ANGPT1 is only upregulated in CAβ3 cells (FC = 1.76), and, in addition to having a role in Schlemm canal development, it has been mapped to the CLC1D glaucoma locus." (PMID 34440692, 2021). "Our data highlight the central role of ANGPT1-TEK signaling and TM-SC crosstalk in IOP homeostasis and provide new candidates for SC-targeted glaucoma therapy." (PMID 34663817, 2021). "These included Angpt1, Ank, Cadm2, Fmnl2, Plce1, Thsd7a, and Tmtc2 at the novel POAG/glaucoma loci identified in the current study." (PMID 29891935, 2018). "Finally, of further interest is the identification of cell–cell interactions involving ANGPT1-TEK, ICAM1 and IL15RA which were previously attributed to glaucoma and uveitis, respectively." (PMID 36163311, 2022). "As an alternative to ANGPT1-mimetics, inhibition or genetic deletion of PTPRB (VE-PTP), which negatively regulates the TEK receptor, has been studied in animal models and is currently being tested in adult patients with glaucoma." (PMID 34663817, 2021). "Conditional deletion of Angpt1, or both Angpt1 and Angpt2, resulted in mice rapidly developing a severe glaucoma phenotype, characterized by the complete absence of SC, buphthalmos (enlargement of the eyeball), markedly elevated IOP, and severe damage to the neural retina." (PMID 38671671, 2024).
glaucoma (continued). "Tie2 deletion as well as Angpt1;Angpt2 double deletion in mice lead to complete absence of SC, highly elevated IOP, and severe glaucoma." (PMID 36190459, 2022).
malaria (15 papers, 2009 to 2022). Malaria is a serious and sometimes fatal disease caused by a parasite that commonly infects a certain type of mosquito which feeds on humans. "We found that, lower levels of Angiopoietin-1 in women who experienced malaria during pregnancy were associated with specific modifications occurring in the placenta." (PMID 26090803, 2015). "In human CM, high levels of angiopoietin-2 and low levels of angiopoietin-1 are linked to CM severity and studies suggest these angiogenic factors function as prognostic biomarkers that can discriminate severe CM from mild malaria and predict fatal CM outcome." (PMID 24433482, 2014). "High levels of angiopoietin-1 are associated with endothelial stability and aberrant angiopoietin-1 and angiopoietin-2 levels have been proposed as good biomarkers for severe malaria." (PMID 24995009, 2014). "To date, there has been no report or study on the detection and comparative analysis of CXCL10, Angiopoietin-1 (Ang-1), and Angiopoietin-2 (Ang-2) in saliva and blood of malaria patients." (PMID 35836234, 2022). "Angiopoietin-1 and Angiopoietin-2 concentrations were measured in peripheral and placental plasma samples from 70 malaria-infected and 216 control women using commercially available DuoSet ELISA development kit." (PMID 32399088, 2020). "Indeed, the ratio of angiopoietin-1 to angiopoietin-2 has been proposed as a potential marker of severe malaria with prognostic value." (PMID 30249265, 2018). "Previous studies have successfully used endothelial cell activation markers to predict severe malaria, notably using angiopoietin-1 and 2, but their specificity to cerebral malaria, as compared to other severe complications, remains unclear." (PMID 24743550, 2014). "Low angiopoietin-1 and high angiopoietin-2 plasma level are associated with retinopathy, discriminate human CM and severe non-cerebral malaria from uncomplicated malaria, and predict mortality from human CM." (PMID 23630573, 2013). "In addition to cytokines, others biomarkers have been used to discriminate cerebral malaria from uncomplicated malaria, such as serum angiopoietin-1 and -2 (ANG-1 and ANG-2)." (PMID 22028888, 2011). "Angiogenic factors such as angiopoietin 1 (Ang-1) and angiopoietin 2 (Ang-2) are biomarkers produced during activation and dysfunction of the vascular endothelium in non-infectious as well as infectious diseases, including malaria." (PMID 25275496, 2014).